PLG (plasminogen)
Diseases named in the same sentence as PLG in open-access papers (continued):
Sharing a sentence is not in itself a finding about the gene and the disease.
ischemic stroke (17 papers, 2016 to 2025). A stroke disorder caused by obstruction of blood flow to the brain, due to thrombotic (local blood clot formation) or embolic (due to a blood clot or other material traveling from another site) event. "Fibrin is one of the main components of blood clots causing ischemic stroke and is the target of rtPA upon activation of plasminogen in the clot." (PMID 36297588, 2022). "Fibrin is one of the main components of blood clots causing ischemic stroke and is the target of rtPA upon the activation of plasminogen in the clot." (PMID 36297588, 2022). "Intravenous recombinant tissue plasminogen activator (t-PA) administration is the standard reperfusion therapy for acute ischemic stroke within 4.5 h of onset; t-PA induces thrombus dissolution by activating plasminogen into plasmin." (PMID 39911452, 2025). "With the cleavage of plasminogen, the tPA produces the active enzyme of the plasmin, which in turn dissolves fibrin-based clots in ischemic stroke." (PMID 38831867, 2024). "Alteplase exhibits specificity for fibrin, primarily targeting plasminogen and fibrin in the coagulation process, with relatively minimal impact on other biological molecules (pharmacokinetics of alteplase in treating ischemic stroke)." (PMID 39233682, 2024). "SMTP congeners with both plasminogen modulation activity and anti-inflammatory activity ameliorate various aspects of ischemic stroke in rodents and primates." (PMID 33477998, 2021). "In ischemic stroke, the combination of plasminogen modulation and sEH inhibition is essential for excellent pharmacological efficacy." (PMID 33477998, 2021). "Unfortunately, the intravenous administration of plasminogen activators remains the best and the only treatment for ischemic stroke, while timing is the key to success." (PMID 32265656, 2020). "Plasminogen is essentially present in both blood and the brain under most pathologic brain scenarios, especially together with rt-PA during its utilization in ischemic stroke." (PMID 26834557, 2016). "Thus, drugs, such as tissue plasminogen activator (tPA), which catalyzes the conversion of plasminogen to plasmin and thereby dissolves clots, are used to treat ischemic stroke." (PMID 34578651, 2021). "The regulation of plasminogen activation by astrocytes may have important repercussions in pathological conditions, and notably in ischaemic stroke." (PMID 28417010, 2017). "For example, some of the differentiation proteins, such as SERPINA3 and CRP involved in inflammatory/acute-phase response, as well as FGA and PLG involved in blood coagulation, were associated with the cardioembolic, large-vessel, and lacunar ischemic stroke subtypes, but not with CBS deficiency." (PMID 31242583, 2019). "Our results indicate that the expression of PLG and PROS1 was elevated in ischemic stroke patients due to excessive blood clotting in ischemic stroke patients, which may be increased by the feedback mechanism that reduces blood clotting to maintain homeostasis." (PMID 32466277, 2020).
angioedema (15 papers, 2016 to 2025). Swelling involving the deep dermis, subcutaneous, or submucosal tissues, representing localized edema. "Comparing our family with the recently published patients with HAE associated with a PLG gene mutation (HAE-PLG), the age of onset, clinical presentation and frequency of angioedema of all affected members of our family are in line with these previous reports." (PMID 30809376, 2019). "Low CPN activity could increase the risk of angioedema via a number of mechanisms, including slowing the degradation of kinins, slowing the degradation of anaphylatoxins, or downregulating activation of plasminogen." (PMID 40053270, 2025). "However, one form of angioedema has been associated with a mutation in the plasminogen gene which renders plasminogen more susceptible to activation by tPA and uPA." (PMID 37762481, 2023). "Targeted re-sequencing of five HAE-associated genes (SERPING1, F12, PLG, ANGPT1, and KNG1) was performed in 212 ACEi/ARB-induced angioedema patients recruited in Germany/Austria, Sweden, and Denmark, and in 352 controls from a German cohort." (PMID 35923707, 2022). "The concept of a link between plasminogen activation and the contact system helps us to explain the inflammatory side effects of fibrinolytic therapy, presenting as angioedema or tissue edema." (PMID 31507620, 2019). "Other genetic determinants of angioedema states include mutations of factor XII (FXII) and plasminogen genes (F12, PLG), presumably leading to fibrinolysis activation." (PMID 30333824, 2018). "Neurologists repeatedly reported angioedema, which is presumably mediated via bradykinin, as a side effect of plasminogen activators given to patients with ischaemic stroke." (PMID 27122021, 2016). "Angioedema might be the result of interaction of plasmin (after conversion of plasminogen to plasmin) with any of the components of the bradykinin-forming cascade to augment bradykinin formation." (PMID 40053270, 2025). "The links between plasminogen activation and angioedema were revised in detail by Maas." (PMID 33560480, 2021). "This suggests that their angioedema episodes might have originated from inadequate inhibition of plasminogen activation and bradykinin formation downstream activated FXII." (PMID 27122021, 2016). "In the context of ACEi/ARB-induced angioedema, a plausible hypothesis is that decreased plasma plasminogen levels lead to naturally lower bradykinin levels, in which case this variant may be protective against bradykinin accumulation during treatment with ACEi/ARB." (PMID 35923707, 2022). "Genetic testing of angioedema is primarily focused on detecting alterations in the DNA of genes encoding proteins that are part of the complement, fibrinolysis, coagulation, kinin, and vasculature systems, including C1-INH (SERPING1), FXII (F12), plasminogen (PLG), or angiopoietin-1 (ANGPT1)." (PMID 33560480, 2021). "Therefore, consideration should be given to whether a PLG defect should be investigated in all cases of ACE inhibitor-induced angioedema." (PMID 30809376, 2019). "Apart from these cases, hereditary angioedema is explained by other genetical defects affecting factor XII, angiopoietin-1, plasminogen, and kininogen 1 genes." (PMID 40599632, 2025). "The results support a role of PLG K330E in the pathogenesis of HAE and suggest that genetic testing be considered as an approach to diagnose patients with unexplained angioedema." (PMID 31131012, 2019). "In conclusion, the present analyses identified no known disease-causing HAE variant in SERPING1, F12, PLG, ANGPT1, or KNG1 in a cohort of around 200 patients with ACEi/ARB-induced angioedema." (PMID 35923707, 2022). "The described patients had low plasminogen activity in plasma but angioedema was not reported." (PMID 32066472, 2020).
hereditary angioedema (14 papers, 2019 to 2026). Hereditary angioedema (HAE) is a genetic disease characterized by the occurrence of transitory and recurrent subcutaneous and/or submucosal edemas resulting in swelling and/or abdominal pain. "The group will then develop pathogenicity classification rules to curate variants in genes responsible for Hereditary Angioedema with normal C1-INH (nl-C1-INH-HAE), such as F12, PLG, ANGPT1, KNG1, MYOF, and HS3ST6 (OMIM: 610618, 619360, 619361, 619363, 619366, 619367)." (PMID 38124188, 2023). "Hereditary angioedema can occur with normal C1-INH, due to mutations in other genes involved in bradykinin overproduction, e.g. factor XII (Hageman Factor), plasminogen gene, angiopoeitin-1 gene and kininogen-1 gene, but there are still many unclassified cases of hereditary angioedema." (PMID 36238930, 2022). "However, substitution of the same residue by Thr in PLG/R70T is predicted as possibly damaging and, interestingly, the PLG/R70T substitution has been flagged as having a potential association with PDI (RCV001334374.1) and hereditary angioedema (RCV002493731.1)." (PMID 38984351, 2024). "Below, we report the known fibrinolytic system alterations occurring in some different forms of hereditary angioedema (HAE) and the central role that plasminogen activation cascade plays in each of them." (PMID 33535668, 2021). "Hereditary angioedema (HAE) in patients with normal C1 inhibitor (C1-INH) and the c.988A > G (p.Lys330Glu; p.K330E) variant in the plasminogen gene (HAE-PLG) is associated with skin swellings, abdominal pain attacks, and the risk of asphyxiation due to upper airway obstruction." (PMID 32066472, 2020). "There is no genetic association or family history of angioedema in AAE-C1-INH; this is in contrast to the types of hereditary angioedema (HAE) which are caused by or associated with specific mutations in the genes coding for C1-INH, factor XII, plasminogen or angiopoietin." (PMID 30866985, 2019). "Hereditary angioedema due to C1 Inhibitor deficiency shares a common kinin dependency with other HAE situations: F12-HAE, PLG-HAE, KNG1-HAE, ANGPT1-HAE, and HS3ST6-HAE, but not with MYOF-HAE, U-HAE." (PMID 35958943, 2022).
Alzheimer disease (13 papers, 2015 to 2024). A progressive, neurodegenerative disease characterized by loss of function and death of nerve cells in several areas of the brain leading to loss of cognitive function such as memory and language. "Using a mouse model of Alzheimer’s disease (AD), we recently showed that plasma PLG deficiency is protective against AD pathology and drastically decreases the brain’s innate immune response." (PMID 31462325, 2019). "In control surfaces (a), we identified proteins associated with ATP synthesis, plasminogen-activating cascade, Huntington and Alzheimer diseases, inflammation mediated by chemokine and cytokine, integrin and cadherin signaling pathways, cytoskeletal regulation, and blood coagulation." (PMID 33880662, 2021). "The proteins forming amyloids in hydrophobic LCRs were also involved in many other pathways and cascades such as plasminogen activating cascade, cadherin signaling pathway, Wnt signaling pathway and Alzheimer disease-presenilin pathway." (PMID 30397544, 2018). "Pathways commonly identified in resected tissues (integrin signaling, inflammation, gonadotropin releasing hormone receptor, Alzheimer disease-presenilin and plasminogen activating cascade) were also frequently found in the cell lines studied." (PMID 26279647, 2015). "Interestingly, both the amyloidogenic peptides hIAPP and amyloid beta (Aβ; the unique constituent of brain amyloid in Alzheimer’s disease) can bind to tPA and substitute for fibrin in the tPA activation of plasminogen." (PMID 39245780, 2024). "Other significantly enriched pathways were the plasminogen activating cascade, the Alzheimer disease–presenilin pathway, blood coagulation, the cadherin signaling pathway, the transforming growth factor beta (TGF–beta) signaling pathway and the Wnt signaling pathway." (PMID 31878157, 2019).
Hypertension (13 papers, 2009 to 2025). The presence of chronic increased pressure in the systemic arterial system. "PAI-1 suppresses the conversion of plasminogen into plasmin and prevents fibrinolysis, which leads to damage of endothelial membranes and the risk of developing AS and hypertension." (PMID 41226575, 2025). "In mice, PAI-1 protects against cardiac fibrosis during hypertension by inhibiting the urokinase-type plasminogen activator (uPA)-mediated activation of plasminogen (Pg) and limiting plasmin (Pm) generation." (PMID 36982525, 2023). "On the other hand, out of five Finnish families with PLG variants, in family UHF48 only one of two affected individuals had asthma, as well as hypertension and psoriasis." (PMID 32929111, 2020). "In animal models, plasmin activity is increased in response to acute injury and absence of uPA or plasminogen inhibits cardiac collagen deposition in response to ischemia, hypertension and myocarditis." (PMID 23536772, 2013).
hypoplasminogenemia (13 papers, 2015 to 2025). "A human plasma-derived plasminogen concentrate (Ryplazim) has been Food and Drug Administration-approved for the treatment of type 1 plasminogen deficiency; however, it requires frequent dosing every 2 to 4 days." (PMID 41169534, 2025). "On the other hand, approximately 50 rare and ultra-rare PLG missense variants have been reported to cause PD as homozygous or compound heterozygous variants, often leading to a debilitating disease known as ligneous conjunctivitis." (PMID 38984351, 2024). "PDI, also known as true PLG deficiency or hypoplasminogenemia, is a genetic disease characterized by low or undetectable PLG antigen." (PMID 38984351, 2024). "Other phenotypes linked to other variants in the PLG gene are hypoplasminogenemia and dysplasminogenemia." (PMID 32066472, 2020). "In type I PLG deficiency, also known as hypoplasminogenemia, PLG activity (PLG:A) and PLG antigen (PLG:Ag) levels are decreased, whereas in type II PLG deficiency, also known as dysplasminogenemia, PLG:A levels are decreased despite normal PLG:Ag levels." (PMID 37065478, 2023). "There are two types of plasminogen deficiency: hypoplasminogenemia (type I PLG deficiency), in which level and activity of PLG are reduced and dysplasminogenemia (type II PLG deficiency), in which the level of immunoreactive PLG is within normal range, but the specific activity of PLG is reduced." (PMID 25971786, 2015). "Plasminogen deficiency type 1 (PLGD-1, hypoplasminogenemia) is an ultra-rare, lifelong disease associated with development of fibrinous lesions in multiple organ systems." (PMID 39372655, 2024). "Further, SNPs rs73015965 (PLG K38E) and rs148685782 (FGG A108G) associated with type I plasminogen deficiency and reduced levels of fibrinogen, respectively, were common only in the EUR population." (PMID 35337356, 2022).
myocardial infarction (12 papers, 2011 to 2025). Gross necrosis of the myocardium, as a result of interruption of the blood supply to the area, as in coronary thrombosis. "Apo (a) has homology with plasminogen and correlates with an increased risk of myocardial infarction." (PMID 33407609, 2021). "Plasminogen activation by uPA is known to be required for normal tissue remodelling, including in myocardial infarct healing, skeletal muscle regeneration and vascular wound healing." (PMID 34876572, 2021). "Plasminogen activators such as recombinant t-PA are important drugs treating acute thrombotic stroke and myocardial infarction." (PMID 22230042, 2012). "Tissue plasminogen activator is a protease that converts plasminogen to plasmin and is used to treat pulmonary embolism, myocardial infarction and stroke." (PMID 21211066, 2011). "Additionally, extracellular matrix (ECM) proteins, including vitronectin (VTN), plasminogen (PLG), and fibrinogen beta chain (FGB), displayed significant fold changes and were strongly associated with early myocardial infarction." (PMID 41399465, 2025). "Plat encodes tissue-type plasminogen activator (t-PA), which converts the zymogen plasminogen into proteolytically active serine protease plasminogen that degrades fibrin clots and has been shown to be an effective acute treatment in acute myocardial infarction." (PMID 28209124, 2017).
melanoma (11 papers, 2000 to 2024). A malignant, usually aggressive tumor composed of atypical, neoplastic melanocytes. "•Proteins linked to melanoma development (PRG4, APOC4, SERPIND1, VWF, TNC and PLG) were identified in the plasma-derived EVs of patients with melanoma." (PMID 39405606, 2024). "Proteins (APOC4, PRG4, PLG, TNC, VWF and SERPIND1) and metabolites (lyso PC a C18:2, PC ae C44:3) previously associated with melanoma pathogenesis were identified as relevant in differentiating between disease stages." (PMID 39405606, 2024). "Beside the MMP family, plasminogen/plasmin system is largely involved in melanoma progression and metastasis." (PMID 25668817, 2015). "Two main proteolytic cascades are involved in melanoma development, the plasminogen activation system and the MMPs family." (PMID 20959825, 2010). "Two classes of proteinases have been shown to be involved in melanoma invasion: the matrix metalloproteinases (MMPs) and the plasminogen activation system." (PMID 20959825, 2010). "The role of plasminogen in the ability of human melanoma cells to cross a human blood-brain barrier model was studied on a transwell system." (PMID 16524486, 2006). "When we pretreated the wild type mice with EACA, a plasminogen inhibitor, prior to intracarotid injection of melanoma cells the brain metastases were also smaller and these animals survived longer similar to the plasminogen knockout mice." (PMID 16524486, 2006). "Inhibition of plasminogen and plasminogen activators reduced melanoma cell migration in an in vitro model." (PMID 16524486, 2006). "This hypothesis is supported by a study on cutaneous melanoma lesions showing co-localization of TN with plasminogen/plasmin in the invasive front of melanomas." (PMID 38187250, 2024). "A monoclonal antibody targeting a specific melanoma cell surface antigen, melanotransferrin, that exhibits excitatory binding to plasminogen, is one recent example of applying such mechanistic insights in successfully preventing the development of brain metastasis in a laboratory model." (PMID 24281074, 2010). "Collagenase-1 (MMP-1) has been shown to be important in melanoma development and could be activated by the plasminogen system." (PMID 20959825, 2010). "The smaller tumors in the EACA treated and plasminogen knockout mice could be due to inhibition of tumor growth in the brain once the melanoma cells reached there or inhibition of tumor cells moving across the blood-brain barrier." (PMID 16524486, 2006). "Thus, we hypothesised that EDPs could enhance melanoma invasion by inducing pro-MMPs expression, whose activation could occur through the plasminogen activation system." (PMID 20959825, 2010). "Taken together, our data demonstrate that activation of TGFβ or plasminogen by IGF2R is not necessary for melanoma invasion." (PMID 38750105, 2024). "Due to this reasoning, we directly tested whether TGFβ and plasminogen were involved in melanoma invasion and we observed that neither of the activated factors alone were able to restore melanoma invasion upon IGF2R knockdown." (PMID 38750105, 2024). "SKMEL28 melanoma cells were cultured with or without plasminogen and/or aprotinin." (PMID 25668817, 2015).